EPCAM (epithelial cell adhesion molecule)
Diseases named in the same sentence as EPCAM in open-access papers (continued):
Sharing a sentence is not in itself a finding about the gene and the disease.
cancer (continued). "Cancer cells were identified with canonical markers of LUAD and alveolar epithelial cells (e.g., SFTPB, SFTPC, EPCAM, NAPSA, and NKX2-1)." (PMID 35874770, 2022). "The CM coating possessed an epithelial cell adhesion molecule (EpCAM), N-cadherin and CD47, which are crucial for homologous adhesion to cancer cells and immune escape." (PMID 36139623, 2022). "The actual contribution of EPCAM to tumorigenesis and its prognostic potential for various cancers remain to be explored, which may be mediated via interaction with self-related signaling and other proteins in the plasma membrane, regulation in cancer stem cells, or DNA methylation." (PMID 36131343, 2022). "We also characterized the MIAPaCa2 cancer stem cells for the expression of the typical surface stem cell markers, namely CD44, CD133, and EpCAM." (PMID 35634239, 2022). "A number of EV membrane proteins, including CD147/basigin and EpCAM, have been selected to pair with the EV markers CD9 or CD63 as biomarker panels for CRC and have been successfully tested for effective cancer detection using blood specimens." (PMID 36612172, 2022). "Another pan-cancer marker was proposed for the diagnosis of HCC and CCA, such as EpCAM+ CD147+ EVs which were increased in HCC, CCA, and other cancers." (PMID 36555854, 2022). "Thus, EpCAM may be better for high proliferation and metastasis of cancer cells." (PMID 35205714, 2022). "Gene expression and protein abundance for EpCAM/EpCAM, ESR1/ER, PGR/PGR, GATA3/GATA3 were detected in cancer epithelial cells." (PMID 36307545, 2022). "Specifically, numerous aptamers target cancer-specific signature markers such as human cluster of differentiation antigen 133 (CD133), CD44, and EpCAM." (PMID 36559056, 2022). "The decreased expressions of β-catenin-dependent cancer stem cell markers (CD44, EpCAM, Notch 1, and Oct4) advocated for the inhibition of metastatic progression." (PMID 36362950, 2022). "The epithelial cell adhesion molecule (EpCAM, CD326), a cancer biomarker, is a glycoprotein with an extracellular, transmembrane, and cytoplasmic domain." (PMID 36428553, 2022). "For post-prostatectomy cancer patients with baseline PSA levels ≤ 1 ng/ml and high EpCAM-expressing, high dose adecatumumab treatment delayed disease progression." (PMID 36369033, 2022). "These cell populations were further analyzed by using Lamp1PM expression in combination with a set of canonical markers distinct for cancer and stromal cells (i.e., desmin, Ki67, Sca1, Sma, Pcam1, CD44, Lyve1, and EpCam)." (PMID 36127469, 2022). "Emerging studies have focused on pan-cancer circulating protein markers such as EpCAM and carcinoembryonic antigen (CEA); both proteins were found to be highly enriched in exosomes derived from colorectal adenomas and cancers." (PMID 36109501, 2022). "Among HCCs with Wnt/β-catenin activation, some show an aggressive phenotype that is positive for EMT transcription factors and cancer stem cell markers, including CK19, EpCAM, and SALL4." (PMID 35053606, 2022). "EGF/EGFR signaling triggered the release of EpEX from cell-surface EpCAM, after which the shed EpICD bound with EGFR to stabilize PD-L1 through the EGFR/ERK pathway in cancer cells." (PMID 36369033, 2022). "As a multi-functional transmembrane protein, EpCAM is involved in the regulation of cell adhesion, stemness, proliferation, and epithelial-to-mesenchymal transition (EMT) of carcinoma cells." (PMID 35517503, 2022). "In our study, cancer stemness markers such as CD44, Nanog, EpCAM showed increased expression in sorafenib-resistant HCC cells." (PMID 34473785, 2021). "Epithelial cell-activating molecule (EpCAM, CD326) is a cell surface protein that is a prominent cancer biomarker and therapeutic target due to its overexpression on epithelial tumors." (PMID 34575064, 2021).
cancer (continued). "In a new sandwich-type biosensor developed for cancer diagnosis, functionalized magnetic beads with anti-CD63, anti-EpCAM, and horseradish peroxidase catalysis were applied." (PMID 34940275, 2021). "Specifically, cancer cell line conditioned media containing exosomes and free proteins were first incubated with three different fluorescent aptamers against CD63, EpCAM and MUC1 on AuNPs (~ 9.2 nm)." (PMID 34855021, 2021). "At the same time, CTCs express cancer stem cell markers, such as CD90, CD133, EpCAM, CK19 and Nanog, etc., which supports the concept of circulating cancer stem cells (CSCs) as the cell origin for the wide spreading of HCC in the body." (PMID 33440657, 2021). "This technique identified cell clusters that, through marker genes, included cancer cells—markers EpCAM, KRT8, KRT18, and KRT23, fibroblasts—marker COL1A1 (cancer cells, 4389 cells; fibroblasts, 2549 cells)." (PMID 34026600, 2021). "EpCAM and vimentin, two prototypic epithelial and mesenchymal markers in EMT and EndoMT, are of particular clinical values in cancer patients." (PMID 34455700, 2021). "Both EPCs and CSCs expressed epithelial lineage markers EPCAM and CDH1/E‐CADHERIN at higher levels than did other cell types, suggesting their potential linkage of the cancer EPC types." (PMID 33898197, 2021). "They both contained low proliferative AD cells with an additional strong EpCAM, CD24, CD133 staining, suggesting a cancer stem cell phenotype." (PMID 34060699, 2021). "EVs were isolated from 80 serum samples from healthy individuals and cancer patients via polyethylene glycol (PEG)-based precipitation and immunoaffinity separation using antibodies against CD9, CD63, CD81, and EpCAM." (PMID 33808296, 2021). "Like the EpCAM-based kit, healthy people have a maximum of 1 CTC detected, while cancer patients have usually more than 1 CTCs." (PMID 33717672, 2021). "A recent study showed that GRHL2 is a key player in EMP and other studies indicated that GRHL2 directly regulates EpCAM and RAB25 expression, which are correlated with cancer progression." (PMID 34771571, 2021). "Despite a distinctive expression pattern of EpCAM during EMT in normal differentiation with an exclusion in mesodermal cells, the actual role of EpCAM in EMT in cancer remains controversially discussed." (PMID 34693227, 2021). "As in the literature, the cancer stem cell (CSC) subtypes HepG2 and Huh7 were determined with the presence of EpCAM+ cells where CD133+ cells were also noticed in Huh7." (PMID 34679523, 2021). "Autocrine IGF-1 signaling is responsible for regulating cancer stem cell (CSC) related markers (e.g., CD44+, ALDH+, and EpCAM+) in MHCC97H cells." (PMID 33669204, 2021). "It is worth noting that LR004-VC-MMAE also downregulated cancer stemness-related genes, such as Oct4, Sox2, KLF4 and EpCAM." (PMID 34879870, 2021). "We compared the CTC counts with both EpCAM and CSV methods from the same blood drawing in 91 cancer patients and only results from the PDAC patients show statistical significance." (PMID 33717672, 2021). "CD47 is a cell surface receptor that regulates macrophages from attacking healthy cells and is known to be overexpressed in cancers; B2M is a marker on MHC class 1 molecules; and EPCAM is a transmembrane receptor on epithelial cells that aids cell adhesion." (PMID 33690223, 2021). "The genes selected included epithelial (KRT5, CDH1, EpCAM), mensenchymal (VIM, SNAI1, TWIST), stem (ALDH1A1, PROM1), breast specific (ESR1, PALB2) and other genes related to cell cycle or other cancer pathways (CCND1, CTNNB1, Ki67, etc.)." (PMID 34071445, 2021). "Further, cells positive for pluripotency, stemness and cancer stem cell niche markers SOX2, ALDH1A1, EPCAM, LGR5 and PORCN were also significantly expanded in Ahr-deficient lesions along the time window analyzed." (PMID 34439225, 2021).
cancer (continued). "In some cancer types, membranous EpCAM expression is lost, while increased cytoplasmic and nuclear expression is present, suggesting that RIP of EpCAM has occurred." (PMID 34209658, 2021). "We excluded the presence of other cell types including cancer cells, immune cells, and endothelial cells by staining with the corresponding markers α-fetoprotein (AFP), epithelial cell adhesion molecule (EpCAM), cluster of differentiation 45 (CD45), and CD31." (PMID 32932015, 2021). "They used their biosensor to screen two exosome biomarkers (CD9 and CD63) and four cancer biomarkers (CD24, CD44, EpCAM, and human epidermal growth factor receptor 2 (HER2))." (PMID 34940275, 2021). "Recently, disseminating hybrid E/M CSCs that co-express EpCam, Vimentin, and CD24 have been observed in human cancer specimens, thus proving that a hybrid E/M CSC-like state is predictive of metastasis." (PMID 34830900, 2021). "Four bio-orthogonal click probes modified with trans-cyclooctene (TCO) were designed to enable the specific targeting of three cancer proteins (EGFR, EpCAM and MUC1) and one generic EV marker (CD63)." (PMID 34855021, 2021). "LR004-VC-MMAE also inhibited the activation of EGFR signaling and the expression of cancer stemness marker genes such as Oct4, Sox2, KLF4 and EpCAM." (PMID 34879870, 2021). "Our results show that the majority of our cells come from luminal epithelial cells as expected, with high accessibility to cancer markers AMACR and EPCAM." (PMID 34911933, 2021). "In the NF-κB signalling pathway, NF-κB p65 and Akt Epithelial cell adhesion molecule (EpCAM) promoted EMT, which initiates metastasis by endowing cancer cells with radio-resistance." (PMID 34298701, 2021). "Compared with that in the normal tissues, the expression of CD24, CD90, EpCAM, CACNA2D1, and CD133 was found highly expressed in the cancer tissues." (PMID 33707423, 2021). "We identified 559 cancer cells according to epithelial and cancer markers including KRT19, KRT7, EPCAM, SOX9, and KRT23." (PMID 34326696, 2021). "CSCs were characterized by the expression of the stem cell markers TWIST, the epithelial cell adhesion molecule (EPCAM), the transcription factors SNAI1 (SNAIL) and SNAI2 (SLUG) and cancer markers such as CD44 and prominin-1 (CD133)." (PMID 34445612, 2021). "Many different signaling proteins and transcription factors, including those that have prominent roles in cancer initiation and progression and EMT, have been shown to either directly or indirectly silence EpCAM promoter activity and expression during EMT." (PMID 34209658, 2021). "This immune-droplet digital polymerase chain reaction (iddPCR) amplification method enabled the multiplexed profiling of EV proteins, e.g. EGFR, EPCAM, PD-L1, CD4, CD8, GZMB, TCF7 derived from cancer cell lines." (PMID 34855021, 2021). "Wnt-β-catenin signaling, which is frequently upregulated in cancer and promotes EMT, can stimulate EpCAM expression." (PMID 34209658, 2021). "This Food and Drug Administration (FDA)-approved first-generation instrumentation relied on a single CSM epithelial cell adhesion molecule (EpCAM) to capture CTCs, followed by CTC enumeration to provide cancer prediction, prognosis, and clinical outcomes." (PMID 34829483, 2021). "Typically, immunomagnetic cell isolation devices use epithelial markers, mostly EpCAM, for CTC detection neglecting the fact that cancer cells undergo morphological changes during epithelial-to-mesenchymal transition (EMT) and the reverse process (MET)." (PMID 34829387, 2021). "Several other CSC biomarkers & effectors, such as TWIST1, ALDH, EpCAM, glucose, and transporters (GLUTs), were also used as CSC targets for cancer therapy, which largely depend on the specific cancer types." (PMID 34959397, 2021).
cancer (continued). "In a similarly designed study, AdnaTest, which identifies CTCs based on reverse transcriptase-PCR (RT-PCR) amplification of cancer-specific markers such as EGFR, CEA, and EpCAM, demonstrated increased sensitivity when compared with CellSearch®." (PMID 34572297, 2021). "In this study, we found that MKL-1 not only promoted the stem cell characteristics of cancer cell MGC-803, but also played a regulatory mechanism through the miR-17/CD44/EpCAM pathway." (PMID 34239355, 2021). "The inflammatory infiltrate was more intense in poorly differentiated carcinomas and triple-negative carcinomas in which the expression of E-cadherin and GRHL2 was reduced, while EpCAM was overexpressed." (PMID 34680248, 2021). "EpCAM (Epithelial Cell Adhesion Molecule; CD326) is a surface glycoprotein expressed in developing and adult epithelia, and selected carcinomas." (PMID 33525555, 2021). "Endocytosis and membrane recycling of EpCAM were confirmed in mF9 cells, E14TG2α ESC, and Kyse30 carcinoma cells." (PMID 34693227, 2021). "Nevertheless, the CellSearch system (CS) which based on EpCAM-related capture of CTCs is standardized, time-efficient and provides clinically relevant results for CTC detection in a wide range of carcinoma patients." (PMID 34111181, 2021). "The overexpressing h-jou transfected cells were also enriched in potential cancer stem cell (CSC) markers, including SOX4, SOX8, CD44, MSI-2, EpCAM, and others." (PMID 33225905, 2020). "A panel of four pan-cancer markers (EGFR, EPCAM, HER2, and MUC1) and three putative PC markers (GPC1, WNT2, and GRP94) were investigated individually and together in plasma-derived exosomes." (PMID 33297544, 2020). "Cell surface oncoproteins, such as CD326/EpCAM, EGFR, and programmed cell death-ligand 1 (PD-L1), are often released from cancer cells by two mechanisms including secretion in exosomes and protein shedding by proteinases." (PMID 32150875, 2020). "Activation of Wnt/beta-catenin signaling enriched the EpCAM+ cell population, whereas RNA interference-based blockage of EpCAM attenuated CSC activities in cancer cells." (PMID 32814771, 2020). "Cancer cells increase the SNAI1 and TWIST expression, and then lose their epithelial markers, such as E-cadherin, epithelial cell adhesion molecule (EpCAM), and acquire through the expression of vimentin and N-cadherin, mesenchymal markers." (PMID 33339353, 2020). "Compared to control cells, OSCC cells in which UBE2C was silenced showed decreased cell proliferation, migration/invasion and colony formation and they exhibited lower expression levels of the following cancer stemness markers—ALDH1/A2, CD44, CD166 and EpCAM." (PMID 32899896, 2020). "Our results indicated that knockdown of UBE2C decreased the expression levels of these cancer stemness markers including ALDH1A2, CD44, CD166 and EpCAM in both Ca9-22 and SAS cells." (PMID 32899896, 2020). "Facilitated by CD9 antibody (for exosome capture), CA-125 (for ELISA detection), EpCAM (for ELISA detection), and CD24 antibodies (for ELISA detection), this platform enabled rapid exosome isolation and in situ non-invasive cancer detection." (PMID 32206116, 2020). "Although EpCAM has not been directly associated with any classical junctional structure, it interacts with different adhesion proteins and this might contribute to its role in cancer progression." (PMID 32764280, 2020). "EpCAM-based capture approaches are, however, rarely efficient for epithelial cancers with downregulated EpCAM expression, likely due to EMT, or cancers of mesenchymal origin." (PMID 32984308, 2020). "Cancer stem cells play pivotal role in malignant cells transformation.Reprogramming genes, such as Nanog, KLF4, EpCAM, c-Myc, Sox2 andp-Oct4 induce the origin of CSCs." (PMID 32779438, 2020).
cancer (continued). "To investigate the functional crosstalk between TGF-β1 and HBx in HPC transformation and HCSC generation, we measured the expression of TGF-β1, HBx, and cancer stem cell (CSC) markers CD90 and EpCAM by IHC staining in a liver tumor tissue microarray." (PMID 31740785, 2020). "Eight mRNA markers (MYC, VEGF, CDX2, CD133, CEA, CK19, EpCAM, and CD24) were found to be more abundant in EVs derived from cancer cell lines compared to control cell lines." (PMID 32042310, 2020). "EpCAM has been implicated in carcinogenesis and is expressed robustly in various types of human epithelial cancers, such as lung, breast, ovarian, cervical and colorectal cancer (CRC), suggesting that it may be a promising target for cancer diagnosis and therapy." (PMID 33154781, 2020). "However, cancer cells undergoing EMT may lose EpCAM expression." (PMID 32260071, 2020). "Increased miR-155 expression was identified in Epithelial cell adhesion molecule (EpCAM)-positive HCC stem cells and inhibition of miR-155 abrogated in vitro cancer phenotypes in these cells." (PMID 32429062, 2020). "The authors also found that stem cells grown on NCPs were able to release exosomes containing epithelial cell adhesion molecules (EpCAM) and heat shock protein 90 (HSP90) that have been closely related to an increased growth of cancers." (PMID 32867142, 2020). "Conversely, the exposure of cancer cells to the ODEP electrical conditions of 7–10 Vpp and 3–5 MHz did not significantly alter the cell viability, cell metabolic activity, and the EpCAM, VIM, and ABCC1 gene expression of cancer cells." (PMID 32560153, 2020). "The significance of this work is to provide a rapid and reliable method to study a specific subpopulation of CSCs, not only limited to the CD13+CD133+EpCAM+ HCC, but also can be a combination of other CSC surface markers or other types of cancer." (PMID 32662250, 2020). "Among EPCAM-positive cells isolated through the GenoCTC platform, CTCs were identified by immunostaining with an anti-CK18 antibody directed towards a cancer epithelial cell marker and an anti-CD45 antibody recognizing a leukocyte marker." (PMID 32486306, 2020). "Two (EPCAM and CDH1) reflect the presence of malignant epithelium in cancer‐replaced nodes and its absence in cancer‐free nodes." (PMID 31755096, 2020). "Evaluation of CSCs parameters in rat carcinoma cells demonstrated a dose-dependent significant decrease in CD24 and EpCam expression in treated groups, when compared to the control group." (PMID 33375383, 2020). "Epithelial cell adhesion molecule (EpCAM), also called CD326, is a transmembrane glycoprotein overexpressed in many carcinomas." (PMID 32257947, 2020). "Also, he underlines the role of cancer specific extracellular vesicles, and how analysis of surface lipids and proteins (e.g. EpCAM) of these vesicles could predict the origin and maybe even the destination of the vesicle and of its cargo, rendering better specificity in cancer diagnosis." (PMID 31142339, 2019). "Epithelial Cell Adhesion Molecule (EpCAM) is another colon CSCs marker that has been reported to be overexpressed in CRC and has an essential role in cancer prognosis and pathogenesis." (PMID 31057717, 2019). "CSCs, depended on cancer types, occupied different markers, such as, SOX2, CD133, epithelial cell adhesion molecule (EpCAM), CD166, CD24, CD29, Lgr5, Kruppel-like factor 4 (Klf4) and ALDH." (PMID 30962766, 2019). "As we enriched EpCAM-positive cells to establish new HOV cell lines, we cannot formally exclude the possibility that we excluded EpCAM-negative cancer cells and included normal epithelial cells." (PMID 31248002, 2019). "Again, the significantly higher proliferation rate observed with STIM1-OE cells over that of EpCAM(+)CD133(+) cells overexpressing both STIM1 and Orai1 (present data) confirms the poor prognosis of several cancer types with overexpressed STIM1." (PMID 31366337, 2019).